CYP4F24P (cytochrome P450 family 4 subfamily F member 24, pseudogene)
Gene: Transcribed unprocessed pseudogene on chromosome 19 (15,760,241 to 15,779,909, reverse strand). Ensembl gene ENSG00000267594.
Diseases named in the same sentence as CYP4F24P in open-access papers:
CYP4F24P is named in the same sentence as 1 disease in open-access papers, as found by Europe PMC text mining. Sharing a sentence is not in itself a finding about the gene and the disease. The quoted sentences say what the papers report.
nasopharyngeal carcinoma (1 paper, 2024). A carcinoma arising from the nasopharyngeal epithelium. "Investigating whether individuals with naturally switched-off GPX1P1 and CYP4F24P are at a higher risk of nasopharyngeal cancer will enable genotyping to identify individuals at elevated risk for nasopharyngeal cancer, facilitating early interventions and improving patient outcomes." (PMID 39315271, 2024). "Of particular interest are the genes CYP4F24P and GPX1P1, both long non-coding RNAs, which are implicated in nasopharyngeal cancer." (PMID 39315271, 2024).